SHMT2 (serine hydroxymethyltransferase 2)
Diseases named in the same sentence as SHMT2 in open-access papers (continued):
Sharing a sentence is not in itself a finding about the gene and the disease.
cancer (continued). "While SHMT1 is expressed to different degrees across carcinomas, there is not yet any report concerning the role of SHMT2 in human HCC." (PMID 27391339, 2016). "We identified a robust upregulation of GLUT1 (SLC2A1), a key rate-limiting factor in the transport of glucose in cancer cells, and genes involved in central glucose metabolism (HK2, ENO1, PKM, and LDHA), PPP (G6PD), and de novo serine biosynthesis pathway (PSAT1, PSPH, and SHMT2)." (PMID 40371988, 2025). "Knocking down SHMT2 significantly blocked the proliferation of LUAD cells, while the proliferation of human bronchial epithelial cells (BEAS‐2B) was not affected, indicating that SHMT2 might be a cancer‐specific target in LUAD." (PMID 38460155, 2024). "However, a previous study has demonstrated that cancer cells with low expression of SLC19A1 (solute carrier family 19 member 1) rely on SHMT1 rather than SHMT2 for 1C unit synthesis." (PMID 39286657, 2024). "SHMT2 is engaged in the metabolism of folate and catalyzes the conversion of serine and tetrahydrofolate (THF) into glycine and 5,10-methylenetetrahydrofolate (5,10-CH2-THF), an important stage in the biosynthesis of the purine nucleotides, which is crucial for sustaining cancer cell proliferation." (PMID 36980194, 2023). "Therapies that target the single-carbon metabolic pathway, such as serine hydroxymethyltransferases (SHMT1 and SHMT2) inhibition, the key enzymes that convert serine to glycine, and lowering entry of monocarbons to the tetrahydrofolate (THF) cycle, are promising for anti-cancer therapies." (PMID 36578477, 2022). "A limitation of this study is that we have not yet demonstrated whether SHMT2 affects cancer cell stemness and activation of the Notch and Wnt signaling pathways through a metabolic function or a non-metabolic function." (PMID 36077112, 2022). "For example, increased expression of rate-limiting one-carbon metabolism enzymes such as SHMT2 and MTHFD1L provides activated methyl groups that are needed for nucleotide biosynthesis and viral replication; these mechanisms have been studied in cancer, and inhibitors are available." (PMID 35891396, 2022). "Indeed, radioisotope assays confirmed that NDI1 overexpression cells failed to alter the ability of metformin to directly engage and block the mitochondrial activity of SHMT2 in living cancer cells (data not shown)." (PMID 34439169, 2021). "In breast cancer, HIF1α and MYC cooperate to drive SHMT2 upregulation, which leads to an increased concentration of nicotinamide adenine dinucleotide phosphate (NADPH) and enhanced redox balance; this in turn facilitates cancer cell growth under hypoxic conditions." (PMID 30367038, 2018). "Furthermore, SHMT2, MTHFD2, and MTHFD1L could accelerate the proliferation of NCI-60 cancer cells." (PMID 40863132, 2025). "In addition, binding of the 5′ untranslated region (UTR) of the SHMT2 transcript to SHMT1 protein has been shown to inhibit the enzymatic activity of SHMT134, suggesting an important link between the mitochondrial and cytosolic one-carbon pathway in cancer progression." (PMID 38331894, 2024). "Thus, inhibiting the activity of SHMT1 or SHMT2 alone is not guaranteed to block cell metabolism, and cancer cells might be compensated by using the other." (PMID 38279895, 2024). "Thus, whereas SHMT2 deletion will fully inhibit mitochondrial translation, SHMT2-targeted drugs might produce relevant anti-cancer effects without achieving the full depletion of mitochondrial 1C units." (PMID 34439169, 2021). "As the cancer inhibitory effects of metformin are cancer cell-autonomous and depend on its ability to inhibit mCI, the refractoriness of SHMT2-KO HAP1 cells to metformin might reflect the requirement for SHMT2 for proper mitochondrial metabolic functioning including the assembly of mCI." (PMID 34439169, 2021). "CRISPR/Cas9-based disruption of SHMT2, but not of SHMT1, prevented metformin from inhibiting total SHMT activity in cancer cell lines." (PMID 34439169, 2021).
cancer (continued). "Furthermore, depletion of LONP1 and ClpP increased cell sensitivity to an SHMT2 inhibitor, suggesting that SHMT2 is a key substrate in the LONP1- and ClpP-mediated proteostasis network and that its protein quality control by mitochondrial proteases may promote cancer cell survival and progression." (PMID 33637676, 2021). "The mitochondrial SHMT2, but not cytosolic SHMT1, is highly expressed in cancer cells and tissues and promotes cancer tumorigenesis." (PMID 30804330, 2019). "This claim is supported by the protein expression of SHMT2 in the HPA, where half the cancer types considered have samples with both high and not detected SHMT2 expression." (PMID 26942765, 2016). "SHMTs comprised two isozymes of SHMT2 and SHMT1 in cells, we performed bioinformatics analysis based on The Cancer Genome Atlas (TCGA) database and found that SHMT2, but not SHMT1, was overexpressed in cancer specimens, with an average 1.522-fold increase compared with controls." (PMID 36806313, 2023). "Moreover, it is exactly that SHMT2 in mitochondria, not SHMT1 in the cytoplasm, was expressed highly in rapidly proliferating cancer cells." (PMID 33163414, 2020). "However, the effect of SHMT2 inhibition appears to depend on the cancer phenotype, in view of the suppression in cell proliferation of rapidly-proliferating LOX IMVI and HeLa cancer cells but not of the slowly-proliferating A498 cell line." (PMID 27391339, 2016). "Notably, to date there are no SHMT2 and ASCT2 inhibitors commercially available for cancer therapy." (PMID 29020998, 2017).
tumor (129 papers, 2012 to 2025). "Elevated SHMT2 protein levels were associated with increased tumor size, positive lymph node metastasis, and more advanced TNM stages." (PMID 40432803, 2025). "Among these, ASCT2, GLS1, LAT1, SLC7A11, SLC3A2, and SHMT2 are key regulators of amino acid metabolism and have been implicated in tumour progression, therapy resistance, and immune evasion." (PMID 41154605, 2025). "Through integrated network pharmacology approaches, serine hydroxymethyltransferase 2 (SHMT2) was identified as a pivotal molecular target implicated in tumor progression." (PMID 40508093, 2025). "And data showed that high expression of SHMT2 was significantly associated with bigger tumor size (p=0.009), positive lymph nodes (p=0.011) and advanced TNM stages (p=0.002)." (PMID 40432803, 2025). "In a study of tumour-bound energy metabolism, SHMT2 was linked to HIF-1α which indicated that serine metabolism regulated the redox response in the anoxic phase." (PMID 38188143, 2024). "Loss of SHMT2 significantly prolonged tumour-free survival of xenografted mice, when compared with mice receiving SHMT2 competent control cells." (PMID 38431691, 2024). "SHMT2 has been reported to be associated with the progression of various tumor cells, such as cell proliferation, migration, invasion and apoptosis." (PMID 37932821, 2023). "In conclusion, higher SHMT2 gene expression and higher serine metabolism in tumour cells are associated with poorer clinical outcomes in pRCC." (PMID 36110969, 2022). "Both MTHFD2 and SHMT2 overexpression have been associated with tumor pathogenesis and poor survival." (PMID 34341479, 2022). "Immunohistochemistry also showed lower expression levels of stemness markers, Notch-related, and Wnt-related genes, including HES1 and CYCLIN D1, in the SHMT2-deficient tumor groups than in the control tumor group." (PMID 36077112, 2022). "In this review, the pivotal roles of SHMT2 in human carcinogenesis are described, highlighting the underlying regulatory mechanisms through promotion of tumour progression." (PMID 34476002, 2021). "In several types of cancer an accentuated deregulation of SHMT2 is observed and is often associated with tumor progression." (PMID 35201488, 2021). "Towards understanding mechanisms of SHMT2 effects on cell proliferation and tumor growth, we sought to identify proteins associated with or proximal to SHMT2 by using proximity biotinylation (BioID) methodology." (PMID 32903271, 2020). "Our results and subsequent studies confirmed that elevated SHMT2 levels are associated with tumor aggressiveness and poor prognosis." (PMID 32903271, 2020). "SHMT2 regulates the activity or expression of proteins that enable tumor cell survival under hypoxia or nutrition deficiencies." (PMID 32903271, 2020). "Two clinical studies have shown that high expression of SHMT2 is associated with tumor aggressiveness and prognosis." (PMID 30367038, 2018). "SHMT2 not only enhanced tumor proliferation, but also associated with immunity." (PMID 37932821, 2023). "Meanwhile, the gene SHMT2 was highly associated with tumor-infiltrating lymphocytes in LUAD." (PMID 33928169, 2021). "For both SHIN1/2 and AGF347, inhibition of both SHMT1 and SHMT2 was essential to their anti-tumor effects, as this prevents metabolic compensation for the loss of SHMT2 activity by reversal of the SHMT1 reaction and the synthesis of glycine and 5,10-methylene THF." (PMID 35008360, 2021). "Also, upregulation of SHMT2 and its association with tumor progression is reported for several types of cancer." (PMID 33637676, 2021). "In tumour samples, elevated expression of SHMT2 was found to be associated with poor prognosis." (PMID 34476002, 2021). "Reduced SHMT2 protein expression and associated glycine reduction, even when effectively potentiated by benzoate treatment was insufficient to inhibit HeLa xenograft tumor growth." (PMID 32903271, 2020).
tumor (continued). "Furthermore, SHMT2 level was closely associated with tumor T stage (P = 0.017) and tumor TNM stage (P = 0.041) in patients with iCCA, but not with age, gender, tumor size, tumor number, pathological grade, vascular invasion, or N stage." (PMID 30228815, 2018). "Moreover, genomic instability caused by nucleotide deficiency in early oncogenesis might be overcome by SHMT2 upregulation to sustain tumor progression." (PMID 27391339, 2016). "Recent studies have highlighted SHMT2's role in promoting tumor cell proliferation, migration, and resistance to apoptosis." (PMID 40432803, 2025). "SHMT2 catalyses serine-to-glycine conversion, sustaining nucleotide biosynthesis and redox homeostasis, especially in hypoxic tumours." (PMID 41154605, 2025). "The high expression of SHMT2 in EC tissues and its critical role in tumor progression make it a promising candidate for use as a diagnostic marker." (PMID 41458606, 2025). "Lactylation enhances PDK1 activity, supporting glycolysis and tumor cell survival, while SHMT2 lactylation regulates one-carbon metabolism." (PMID 41458606, 2025). "Research also revealed that the metabolite succinate enhanced tumor metabolic adaptation by upregulating SHMT2 expression, thereby supporting rapid tumor growth." (PMID 40738465, 2025). "Meanwhile, we found that SHMT2 showed higher expression level in bladder urothelial carcinoma (BLCA) tumor samples compared with adjacent normal samples." (PMID 41347062, 2025). "Collectively, these findings identify mitochondrial SHMT2 as a central driver of metabolic remodeling and tumor aggressiveness in ATC." (PMID 40738465, 2025). "Network pharmacological analysis was employed to identify core target genes, among which SHMT2 was recognized as a critical target for tumor treatment." (PMID 40508093, 2025). "SIRT5 tumor promoting activity is mediated by its substrates involved in metabolic regulation, including serine hydroxy methyltransferase 2 (SHMT2)." (PMID 39215785, 2025). "SHMT2 is an enzyme that can convert serine into glycine and a tetrahydrofolate-bound one-carbon unit, promoting tumor growth by supporting thymidine synthesis and purine synthesis." (PMID 41347062, 2025). "In line with this, SIRT5 knockout or expression of succinylation mimicking mutant of SHMT2 (K280E) led to the suppression of tumor development in vitro and in vivo." (PMID 39215785, 2025). "Serine hydroxymethyltransferase 2 (SHMT2) converts serine into glycine and a one-carbon unit bound to tetrahydrofolate, supporting the synthesis of thymidines and purines, thereby promoting tumor growth." (PMID 39781339, 2025). "Compared with normal gastric cells, the results of Western blotting confirmed higher expression of SHMT2 in tumour cell lines." (PMID 38188143, 2024). "A significant decrease in tumor mass was induced by the stable knockdown of SHMT2 compared to the control, which was measured in the region of interest (ROI) using bioluminescence imaging." (PMID 38331894, 2024). "To explore the effects of SHMT2‐Ser90 phosphorylation on tumor metabolism, we performed untargeted metabolomics to investigate the changes in global metabolites between A549‐WT and A549‐SHMT2‐S90A cells." (PMID 38460155, 2024). "For example, SIRT3 can promote tumor growth by enhancing the deacetylation and thus activity of SHMT2, but it can also exert anti-tumor effects by increasing SOD2 activity and reducing ROS production." (PMID 39763669, 2024). "SHMT2 has been shown in clinical studies that the higher the expression, the more aggressive the tumor is and the worse the prognosis." (PMID 38625586, 2024). "Our study found that in HNSCC, SHMT2 suppresses anti-tumor immune responses by down-regulating CD44 expression and inhibiting T cell activation through MIF." (PMID 38625586, 2024). "High levels of SHMT2 promote L-serine catabolism, resulting in the attenuated proliferation and accelerated death of tumor cells under hypoxia." (PMID 39519335, 2024).
tumor (continued). "Consistently, tumor tissues with high SHMT2 expression showed weak intensity of PTEN staining, while strong PTEN staining was observed in tissues with low SHMT2 expression." (PMID 38272883, 2024). "By increasing SHMT2 expression to promote L-serine catabolism, L-serine pool homeostasis can be disrupted, effectively inducing apoptosis in tumor cells under hypoxic conditions." (PMID 39519335, 2024). "The statistical analysis of the quantified staining results from LUAD tissues divided the tumor samples into two groups according to the level of SHMT2‐pS90." (PMID 38460155, 2024). "H&E staining of lung tissues showed that larger metastatic tumor nodes were formed in the mouse lung with injection of SHMT2-overexpressed BHP10-3 than those of control." (PMID 38272883, 2024). "Since SHMT2 and MTHFD2 were consistently upregulated in undifferentiated thyroid cancer and strongly positively correlated with tumor size, we evaluated the associations of these genes with clinico-pathological features." (PMID 38331894, 2024). "Consistent with the data in vitro, overexpression of SHMT2 dramatically increased the area and number of the mouse lung metastatic tumor nodes, and MK-2206 administration abolished the effect of SHMT2 on enhancing lung metastasis in mice." (PMID 38272883, 2024). "More importantly, we validated this observation in our patient cohort using western blotting and immunohistochemistry of tumor and normal frozen tissues and similarly observed significant overexpression of SHMT2 in HNSCC." (PMID 38625586, 2024). "The results showed that compared with normal tissues, SHMT2 is upregulated in many human tumours including GC." (PMID 38188143, 2024). "Specifically, we demonstrate that mitochondrial 1C metabolism is indispensable for purine synthesis and genetic ablation of SHMT2 inhibits tumour formation capacity of CML cells." (PMID 38431691, 2024). "First, we analysed the difference in SHMT2 expression levels between human tumours and normal tissue through the UALCAN database." (PMID 38188143, 2024). "This correlated with a significant decrease in tumour burden in mice transplanted with KCL22 SHMT2 KO cells." (PMID 38431691, 2024). "Evidently, SHMT2 protein levels were dramatically elevated in tumor tissues compared to those in para-tumor tissues." (PMID 38272883, 2024). "SHMT2 plays a crucial role in human carcinogenesis, highlighting a potential regulatory mechanism that promotes tumor progression." (PMID 38577602, 2024). "SHMT2 inhibition significantly compromises mitochondrial respiration and decreases cell proliferation and tumor size in vitro and in vivo." (PMID 38331894, 2024). "Some studies have even reported that tumor cells required SHMT2 to support tumor growth by maintaining the redox balance and cell survival." (PMID 36806313, 2023). "Some important genes involved, for example, in the synthesis of glycine from serine, such as SHMT2 (serine hydroxymethyltransferase 2), showed increased expression in tumor tissue." (PMID 36831650, 2023). "We found that, in addition to some metabolic and synthetic pathways, SHMT2 was significantlycorrelated with the cellular response to hypoxia, gene upregulation by reactive oxygen species (ROS), the tumor proliferationsignature, and the G2M checkpoint pathway." (PMID 37108312, 2023). "Unexpectedly, knockdown of SHMT2 obviously slowed down tumor growth in nude mice, as evidenced by smaller tumor size and lighter weight." (PMID 37932821, 2023). "Consistent with this, SHMT2 silencing remarkably suppressed the m6A levels of MYC in nude mice tumor tissues." (PMID 37932821, 2023). "VEGF–STAT3, which is directly downstream of HIF1α,is crucial for tumor development.The Western blot analysis revealed that the deletion of SHMT2 impaired the HIF1α expression, which consequently impacted the VEGF–STAT3pathway downstream." (PMID 37108312, 2023). "SHMT2 is highly expressed in many tumors and is considered a potential new target for tumor therapy." (PMID 37204526, 2023).